MIR8069 (microRNA 8069)
Synonyms: MIR8069-2; hsa-mir-8069-2
Gene: MicroRNA gene on chromosome 21 (13,724,189 to 13,724,274, forward strand). Ensembl gene ENSG00000278618.
Homologues: Paralogues in human: hsa-mir-8069-1 (100% identical).